HMGB1 (high mobility group box 1)
Diseases named in the same sentence as HMGB1 in open-access papers (continued):
Sharing a sentence is not in itself a finding about the gene and the disease.
Sepsis (continued). "In this study, we demonstrated the direct role of sepsis mediator HMGB1 in promoting ACE2 expression in alveolar epithelial cells, which may form a positive feedback to accelerate viral infection and host damage." (PMID 33313438, 2020). "Thus, HMGB1 offers a relatively wider time window for clinical treatment of sepsis patients with progressive inflammation." (PMID 33552058, 2020). "Whether any of these molecules are mediated by HMGB1 or whether HMGB1 promotes the survival of MDSCs through other specific pathways or enhances its immunosuppressive capacity in sepsis is still unknown and needs further research." (PMID 33552058, 2020). "Therefore, HMGB1 exerts an indispensable role in the immune disorder and life-threatening inflammatory syndrome of sepsis." (PMID 33552058, 2020). "Intriguingly, blocking the HMGB1/RAGE axis may ameliorate sepsis-evoked mortality and ALI in mice by attenuating inflammation." (PMID 32089649, 2020). "Given the important role of posttranslational modified HMGB1 (e.g., acetylation) in both sepsis and the Caspase-11–dependent pyroptosis pathway, it is possible that citrullinated HMGB1 by PAD2 could increase its release and further activate Caspase-11." (PMID 33055424, 2020). "We further investigated whether sesamin can similarly alleviate LPS-induced sepsis in vitro through the HMGB1/TLR-4/IL-33 pathway." (PMID 32893702, 2020). "In the present study, we provided a valuable clue that CBP bromodomain inhibitors such as SGC-CBP30 might be used as therapeutic agents for sepsis, which is regulated by HMGB1." (PMID 33603756, 2020). "HMGB1 is associated with illness severity and is persistently elevated in the non-surviving population of patients with sepsis." (PMID 32635454, 2020). "have concluded that HMGB1 could reverse immunosuppression in sepsis, when released at moderate levels." (PMID 33552058, 2020). "Extracellular HMGB1 and its receptors, RAGE, TLR2, and TLR4, have been implicated in mechanisms of many inflammatory diseases, including sepsis, atherosclerosis, and rheumatoid arthritis by induction of senescence-associated secretory phenotype via NF-kB activation." (PMID 33384655, 2020). "Furthermore, extracellular HMGB1 levels in the serum of subjects with sepsis is a late mediator of inflammation for septic shock mice." (PMID 32024151, 2020). "As a late inflammatory mediator that contributes to high lethality in sepsis, HMGB1 may be a relevant therapeutic target for intervention." (PMID 33603756, 2020). "Furthermore, HMGB1 induced neutrophil dysfunction in experimental sepsis by reducing the NADPH oxidase activity, while treatment with anti-HMGB1 Ab in contrast significantly diminished the sepsis-induced neutrophil dysfunction." (PMID 32380958, 2020). "This led to the search for late mediators of lethality in sepsis, and this search yielded high-mobility group box-1 (HMGB1), a nuclear protein that is released by the liver during sepsis that can drive pyroptosis, immune dysfunction, and lethality in sepsis models." (PMID 32328059, 2020). "MiR-205 alleviates sepsis-induced renal injury through the HMGB1-PTEN signaling pathway." (PMID 32412059, 2020). "When initially secreted by innate immune cells at relatively low amounts, HMGB1 might still be pro-inflammatory during the early stages of sepsis." (PMID 32265930, 2020). "Exploring the possible regulatory mechanism between HMGB1 and MDSCs in sepsis may provide new ideas for the immunotherapy of sepsis." (PMID 33552058, 2020). "Persistent inflammatory state, high HMGB1 in plasma after sepsis." (PMID 33658992, 2020). "Studies on both patients with sepsis and sepsis animal model indicated that HMGB1 could facilitate the release of inflammatory cytokines from macrophages, such as: TNF-α, interleukin-6 (IL-6)." (PMID 33552058, 2020). "In addition, treatment with ginsenoside Rh1 reduced the CLP-induced release of HMGB1, sepsis-related mortality and tissue injury in vivo." (PMID 32629817, 2020).
Sepsis (continued). "Our observations also raise the possibility that targeting caspase-11 in sepsis could improve outcomes not only by directly blocking pyroptosis in macrophages and endothelial cells but also by suppressing HMGB1 release from the liver." (PMID 32328059, 2020). "Additionally, investigation showed that platelet-derived HMGB1 stimulated neutrophil extracellular traps (NETs) formation in septic shock patients and sepsis mouse model induced by cecal ligation and puncture (CLP)." (PMID 33552058, 2020). "The inactivation of HMGB1 with specific anti-HMGB1 antibodies increased the survival of animals with severe polymicrobial sepsis, reduced high tidal volume ventilation-induced lung injury, and diminished endotoxin and hemorrhage-induced increases in pulmonary levels of inflammatory cytokines." (PMID 32600307, 2020). "Systemic administration of disulfide HMGB1 reproduced the neuropathology seen after CLP sepsis." (PMID 32265930, 2020). "HMGB1 is considered as a critical regulator of sepsis severity." (PMID 32943679, 2020). "Besides, study has shown that reducing the release of HMGB1 can effectively improve the survival of mice suffering from sepsis." (PMID 33552058, 2020). "Furthermore, in preclinical studies ketamine has been shown to attenuate sepsis-induced acute lung injury via a functional down-regulation of the HMGB1-RAGE pathway." (PMID 32380958, 2020). "Collectively, these results suggest that CBP bromodomain could serve as a candidate therapeutic target for the treatment of lethal sepsis via inhibiting LPS-induced expression and release of HMGB1 and suppressing the pro-inflammatory activity of HMGB1." (PMID 33603756, 2020). "Both HMGB-1 and TGFBIp are proinflammatory mediators that promote vascular leakage in sepsis." (PMID 33193799, 2020). "Systemic HMGB1 levels are increased during the acute stage of sepsis, but persistently elevated for weeks or months in both mice and patients for unknown reasons." (PMID 32265930, 2020). "Interestingly, high mobility group box-1 protein (HMGB1), a crucial late biomarker of lethal systemic inflammation in sepsis, stimulates IL-17A release during myocardial I/R injury." (PMID 32849528, 2020). "It is worth noting that in a sepsis rat model, serum-derived HMGB1 accumulates in the renal tissue and urine and turn renal tubular epithelial cells (TECs) into inflammatory promoter mediators, which facilitate the release of pro-inflammatory cytokines through binding to TLR4." (PMID 33552058, 2020). "Therefore, the specific mechanism of HMGB1/TLRs/RAGE/NF-κB pathways that mediate inflammation in sepsis need further exploration." (PMID 33552058, 2020). "In adult sepsis, novel therapeutic options such as interleukin-22, anti-high mobility group box 1 (HMGB1) monoclonal antibody, vascular endothelial growth factor receptor monoclonal antibodies, and recombinant human thrombomodulin (rhTM) are the focus of preclinical investigation." (PMID 31941991, 2020). "Moreover, therapeutic targeting HMGB1 in sepsis animal models has shown promising results in decreasing proinflammatory cytokine levels and improving outcomes 6-8." (PMID 33061810, 2020). "Furthermore, transcutaneous vagus nerve stimulation reduced systemic HMGB1 levels and improved survival in an experimental sepsis model." (PMID 32380958, 2020). "In mouse models, apoptosis of mouse peritoneal macrophages may be due to the release of HMGB1 in sepsis." (PMID 32983116, 2020). "Myeloid-derived suppressor cells (MDSCs), which are also one of the important cells that play an immunosuppressive effect in sepsis, may connect with HMGB1." (PMID 33552058, 2020). "Moreover, P5 can dose-dependently inhibit HMGB1 release by macrophages and reduce the mortality rate in a mouse model of sepsis." (PMID 33293898, 2020).
Sepsis (continued). "The high mobility group box 1 (HMGB1) is a well-known late mediator of sepsis, secreted by multiple stimuli, involving pathways, such as the mitogen-activated protein kinase (MAPK) and nuclear factor kappa B (NF-κB) pathways, and reactive oxygen species (ROS) under inflammation." (PMID 32655573, 2020). "HMGB1 and other inflammatory cytokines are persistently elevated in sepsis." (PMID 32629817, 2020). "The major source of circulating HMGB1 in sepsis is hepatocytes." (PMID 32328059, 2020). "One potential mechanism by which RSV could inhibit HMGB1 release is by preventing HMGB1 nuclear-cytoplasmic translocation through up-regulating SIRT1 in a sepsis-induced liver injury mouse model." (PMID 33139717, 2020). "HMGB1 in involved in infection, organ dysfunction and immune responses in acute injury and chronic disease, including myocardial infarction, stroke, acute lung injury, acute liver injury, ischemia–reperfusion injury, sepsis, fibrotic disorders, and cancer." (PMID 31092889, 2019). "Extracellular HMGB1 has been confirmed as a damage-associated molecular pattern (DAMP), which plays a part in the development of many clinical diseases, such as ALI/ARDS, sepsis, asthma, and cancer." (PMID 31781288, 2019). "Importantly, in a sepsis induced mouse model it was shown that administration of recombinant HMGB1 induced splenomegaly, lymphocytosis and splenocyte priming." (PMID 30858513, 2019). "Therefore, the increased levels of HMGB1 predict multiple organ dysfunction syndrome (MODS) with fatal consequences of infection; thus, increased systemic HMGB1 is considered a biomarker of sepsis." (PMID 31847111, 2019). "HMGB1, a ubiquitous nuclear protein present in all cell types, can be released into the extracellular milieu as a damage-associated molecular pattern molecule (DAMP) to act as a key endogenous and pathogenic mediator of sepsis." (PMID 30975096, 2019). "Importantly, genetic deletion or inhibition of inflammasome components severely impairs HMGB1 release during sepsis or vascular diseases." (PMID 31336567, 2019). "However, in the current study, HMGB1 increased quickly during the early phase of sepsis, which is 12 h after the model was established and then dropped rapidly, a similar pattern as TNF-α." (PMID 31420571, 2019). "High mobility group box 1 was first reported as a late mediator of lethality in sepsis." (PMID 31333497, 2019). "In both HS and sepsis models, elevated HMGB1 enhanced the inflammatory response." (PMID 31333497, 2019). "High Mobility Group Box-1 (HMGB1) is a non-histone nuclear protein that has been implicated in many pathological processes, from sepsis to ischemia." (PMID 31835864, 2019). "We hypothesized that the administration of HMGB1 inhibitor EP or anti‐HMGB1 antibody could attenuate sepsis‐exacerbated VIDD by repressing HMGB1 signalling." (PMID 31339670, 2019). "HMGB1 may be secreted from macrophages, small intestine, and gut tissue in sepsis, ischemia, and traumatic injury/HS, respectively." (PMID 31333497, 2019). "Clinically, sepsis severity has been shown to correlate with DAMPs; studies have shown that increased serum levels of DAMPs including high mobility group box 1 (HMGB1), extracellular cold-inducible RNA-binding protein (eCIRP), and H3 correspond with increased with disease severity." (PMID 31736963, 2019). "Antagonism of cerebral HMGB1 significantly alleviated sepsis-induced brain injury, indicating that HMGB1 is a major contributor to sepsis-induced brain injury and represents a potential therapeutic target by virtue of its effective neuromodulation of the immune system." (PMID 30881224, 2019). "A series of publications indicated XBJ attenuates HMGB1 expression in sepsis organ injuries." (PMID 31969817, 2019). "Furthermore, stabilin-1–mediated phagocytosis is inhibited by HMGB1 (high-mobility group box 1), a pro-inflammatory mediator of organ damage in sepsis." (PMID 31434355, 2019).
Sepsis (continued). "However, other studies have demonstrated that HMGB1-blocking therapies show beneficial effects in providing significant protection following traumatic brain injury, arthritis, experimental sepsis and liver injury." (PMID 30782181, 2019). "In contrast to early onset inflammatory mediators of sepsis (namely, tumor necrosis factor and interleukin-1), which return to baseline early in murine models, HMGB1 levels remain elevated for at least 4 weeks after experimental sepsis induced by cecal ligation and puncture." (PMID 31892321, 2019). "LPS has been shown to induce HMGB1 release and triggers systemic inflammatory response in sepsis." (PMID 31402909, 2019). "Our findings revealed that Gstp gene knocked caused a significant increase in mouse serum HMGB1 level, suggesting that GSTP might function as a negative regulator in controlling HMGB1 release in sepsis." (PMID 29520271, 2018). "Previous investigations have demonstrated that HMGB1 is a useful marker of severe sepsis, and several reports have demonstrated that once activated and secreted into the extracellular milieu, this cytokine can mediate sepsis-related inflammatory responses." (PMID 30713502, 2018). "Given the selective inhibitory effects of P5 on HMGB1 release and the role of HMGB1 in the pathogenesis of both sterile and infectious inflammatory diseases, we investigated the effects of P5 in murine models of hepatic I/R injury and sepsis." (PMID 29317708, 2018). "Since it has emerged as a key mediator in sepsis and contributes to the high lethality of sepsis, HMGB1-targeting strategies may be effective to treat sepsis." (PMID 29520271, 2018). "Specific inhibition of endogenous HMGB1 with antagonists, such as soluble receptor for advanced end glycosylation products (sRAGE), HMGB1 A box or an anti-HMGB1 antibody (Ab), has been shown to reverse the lethality of established sepsis." (PMID 29696019, 2018). "Similarly, compared with normally fed mice after CLP treatment, serum cytokine and HMGB1 levels were lower in male C57BL/6N mice that underwent alternate day calorie restriction for 8 d before CLP induced sepsis." (PMID 30533222, 2018). "The extracellular HMGB1 was first described to be a late-acting mediator of endotoxemia and sepsis." (PMID 29593748, 2018). "This could be a potential remediation for various vascular inflammatory diseases, such as sepsis and septic shock, via inhibition of the HMGB1 signaling pathway." (PMID 30597896, 2018). "The inhibition of specific inflammatory cytokines such as a tumor necrosis factor (TNF), migration inhibitory factor (MIF), or high mobility group box (HMGB)-1 provided promising results in experimental sepsis, but, they failed in the clinical trials for sepsis." (PMID 29780390, 2018). "The levels of HSP70 and HMGB1 decreased in AKI patients with sepsis who expired." (PMID 30666251, 2018). "Recently, C5a plays an important role in regulating HMGB1 release in sepsis." (PMID 29696019, 2018). "High-mobility group box 1 is a well-known mediator of sepsis." (PMID 29696019, 2018). "In addition, previous studies have shown that HMGB1, an important danger signal molecule, is closely involved in sepsis via Toll-like receptors." (PMID 29176858, 2017). "HMGB1 is considered a late mediator of lethal systemic inflammation in sepsis." (PMID 28484719, 2017). "The results suggested that GL may act as a HMGB1 suppressor to exert its beneficial effects in sepsis." (PMID 28484719, 2017). "In the context of sepsis, HMGB1 may function as a biological ‘switch’ to instigate inflammation resolution and potentially drive immune dysregulation following the acute pro-inflammatory phase." (PMID 28724977, 2017). "However, the real cellular target of salidroside for SIRT1-regulated NF-κB activation inhibition and HMGB1 nucleocytoplasmic translocation inhibition during sepsis still needs to be clarified in the future." (PMID 28931916, 2017).
Sepsis (continued). "Recent studies indicated the roles of extracellular HMGB1 in inflammation-associated disease pathogenesis; the administration of neutralizing anti-HMGB1 antibodies or HMGB1 inhibitors significantly reduces inflammatory conditions in sepsis, arthritis, colitis, and ischemic reperfusion." (PMID 28403838, 2017). "Pre-clinically, administration of neutralising ovine anti-HMGB1 polyclonal antibodies improved survival in murine endotoxaemia and caecal ligation and puncture-induced sepsis models, and altered early cytokine profiles to one which corresponded to patterns observed in the surviving patient cohort." (PMID 28724977, 2017). "As such, HMGB1-blockade may aid in dampening the magnitude of inflammatory signalling in sepsis and leave patients more responsive to further therapeutic immunomodulation." (PMID 28724977, 2017). "HMGB1 inhibitors and neutralizing antibodies significantly increase survival in septic patients, suggesting that it may be a valid therapeutic target for sepsis." (PMID 29258263, 2017). "In addition, serum levels of HMGB1 were elevated with delayed kinetics in sepsis patients showing overwhelmed cellular inflammatory and immune responses, resulting in multiple organ failure, tissue damage, and death." (PMID 28403838, 2017). "In addition, HMGB1, a late mediator of inflammation during sepsis, is essential in the responses of sepsis-induced injury." (PMID 28931916, 2017). "Salidroside significantly and effectively upregulated SIRT1 expression, inhibited the inflammatory cascade reaction, decreased the NF-κB activation and HMGB1 nucleocytoplasmic translocation, reduced the severity of acute lung injury, and improved the survival rate during sepsis." (PMID 28931916, 2017). "GL may protect rats against sepsis by blocking the interaction of HMGB1 with cell surface receptors and HMGB1-mediated inflammatory responses." (PMID 28484719, 2017). "The level of serum HMGB1 is significantly increased in patients with severe sepsis." (PMID 28484719, 2017). "As a late mediator of sepsis, HMGB1 could modulate the inflammatory cascade through interaction with receptors of various cell types and induce activation of intracellular signaling pathways." (PMID 28484719, 2017). "While the role of HMGB1 in the development of immunosuppression and immunoparalysis in sepsis is poorly understood, several potential mechanisms have been described that may contribute to the results described here." (PMID 28724977, 2017). "HMGB1 is a potent mediator of systemic inflammation in sepsis." (PMID 28694564, 2017). "It is becoming apparent that HMGB-1 may be a substance that is more important in the chronic phases of severe sepsis than the initial mediator storm of early sepsis." (PMID 28286376, 2017). "HMGB1 contributes to the high lethality of sepsis via late-acting downstream effectors." (PMID 29258263, 2017). "HMGB1 inhibition significantly improves survival in septic patients and in an animal sepsis model." (PMID 29258263, 2017). "Our studies presented here indicate that administration of anti-HMGB1 pAb to a murine model of severe sepsis alters the pattern of cytokine signalling to a more favourable profile, improves survival, and protects against the development of post-septic immunosuppression." (PMID 28724977, 2017). "Serum high-mobility group box 1 (HMGB1) levels were significantly elevated in surviving sepsis-induced mice for 4–6 weeks, with administration of recombinant HMGB1 to naive mice inducing similar splenomegaly, leukocytosis and splenocyte priming phenotypes as sepsis-induced survivors." (PMID 28535799, 2017). "Organ failure in severe sepsis is speculated to result from disruption of epithelial and endothelial barriers, indeed HMGB1 has been shown to enhance epithelial permeability." (PMID 28186706, 2017).